SCN1A (sodium voltage-gated channel alpha subunit 1)
Diseases named in the same sentence as SCN1A in open-access papers (continued):
Sharing a sentence is not in itself a finding about the gene and the disease.
Dravet syndrome (continued). "A previous study has shown that Dravet Syndrome, with progressive infantile onset epileptic encephalopathy caused by loss-of-function mutations in SCN1A, is correlated with natural loss of Nav1.3 channel expression in brain development, coupled with failure of increased functional Nav 1.1 channels." (PMID 27224030, 2016). "This may be the case, for example, for some SCN1A mutations that were already known in the Dravet Syndrome cases and held responsible for the condition." (PMID 26501104, 2015). "Recurrent mutations of SCN1A have also been observed in Dravet syndrome." (PMID 26029160, 2015). "Mutations of SCN1A are responsible for EIEE6 (Dravet syndrome)." (PMID 26029160, 2015). "Many other missense mutations in SCN1A also contribute to Dravet's Syndrome, but most of the complications of Dravet's Syndrome result from SCN1A mutations caused by frame shift, nonsense, and splice-site mutations, which lead to a truncated protein and haploinsufficiency of SCN1A." (PMID 23662118, 2013). "In addition, identical SCN1A missense or truncation mutations are associated with widely different seizure severities, including intractable seizures of Dravet syndrome, comparatively benign FS, and even asymptomatic family members in some cases." (PMID 19763161, 2009). "Additionally, CACNA1C channels may also be expressed in GABAergic inhibitory interneurons, and their pathogenic mechanisms are similar to the loss-of-function mutations in SCN1A seen in Dravet syndrome." (PMID 41177904, 2025). "Additional evidence implicating PV+ neurons in epilepsy stems from genetic disorders including Dravet syndrome, which is a rare genetic treatment-resistant epileptic encephalopathy, which begins in infancy or early childhood, frequently caused by the loss-of-function mutations in SCN1A." (PMID 38563502, 2024). "Mutations in the SCN1A are associated with Dravet Syndrome (DS, severe myoclonic epilepsy in infancy), a drug-resistant epileptic encephalopathy." (PMID 37873808, 2023). "The causal, major-effect, SCN1A variant may need to act against a broadly compromised genomic background to generate the full Dravet syndrome phenotype, whilst genomic resilience may help to ameliorate the risk of premature mortality in adult Dravet syndrome survivors." (PMID 37006128, 2023). "Moreover, the consequences we have shown of increased Scn1a expression point to the need for quantitative precision in genetic therapies intended to increase SCN1A transcription for treatment of seizures in Dravet syndrome associated with SCN1A haploinsufficiency." (PMID 35551471, 2022). "Dravet Syndrome (DS) is a developmental epileptic encephalopathy caused by heterozygous loss-of-function mutations in the voltage-gated sodium channel (VGSC) gene SCN1A." (PMID 35159264, 2022). "Therefore, in addition to causing cortical seizure activity, Dravet syndrome-associated Scn1a mutations may disrupt the inhibitory modulation of RTN chemoreception." (PMID 36605420, 2022). "Again, extensively studied SCN1A pathogenic variants provide a good model for this concept, since similar variants could lead both to a Dravet syndrome phenotype and to a Generalized Epilepsy with Febrile Seizure plus phenotype (GEFS+) in two different subjects." (PMID 35250806, 2022). "A similar approach was applied to a mouse model of Dravet syndrome (DS), a severe epileptic encephalopathy caused by loss-of-function mutations in SCN1A." (PMID 34414418, 2021). "Dravet syndrome is caused mainly by sodium channel gene SCN1A variants, but due to the use of massively parallel sequencing technologies, a significant number of variants in other genes such as GABRs have been found to arise de novo in EE cases including Dravet syndrome patients." (PMID 34095830, 2021). "In a different study, CRISPR/Cas9 was used to knock-in (KI) a pathogenic, PE promoting, variant of sodium channel, voltage-gated, type I, alpha (Scn1a) to generate a Dravet Syndrome (DS) mouse model." (PMID 34899861, 2021).
Dravet syndrome (continued). "In SCN1A-Dravet syndrome, increased risk of SUDEP may relate to cardiac sodium channel dysfunction." (PMID 34713254, 2021). "Besides the six patients with SCN1A variants who could all be classified as having Dravet syndrome, large phenotypic heterogeneity was noted among patients with PRRT2, KCNQ2, and SCN2A variants." (PMID 31572294, 2019). "Furthermore, modifying alleles may preferentially be found in Dravet syndrome patients with SCN1A mutations that are less deleterious when compared to complete heterozygous loss of function mutations." (PMID 19763161, 2009). "To evaluate the generality of the NMA chemistry, we applied it to modulation of SCN1A exon 20N splicing, a therapeutic strategy for Dravet syndrome." (PMID 42165132, 2026). "CBD reduces the frequency and severity of temperature induced seizures and improves autistic-like social behaviours in the in-vivo mouse model of Dravet syndrome (SCN1A+/-)." (PMID 41099962, 2025). "Based on the clinical course and genetic findings, the patient was diagnosed with Dravet syndrome because of SCN1A haploinsufficiency." (PMID 40903466, 2025). "Conversely, models such as SCN1A mutant mice (Dravet syndrome) demonstrate limited or variable responses to GABA-T inhibition because their underlying pathology reflects sodium channel dysfunction rather than primary deficits in GABAergic inhibition." (PMID 41614796, 2025). "In the SCN1A cohort, most individuals had Dravet syndrome (55/59; 93.2%), the remaining having other SCN1A-related DEEs." (PMID 39882024, 2025). "Eight individuals (6.2%) had died after their last follow-up; four had SCN1A-related Dravet syndrome; the others had CHD2, GNAO1, KCNT1 and NEXMIF-related DEEs." (PMID 39882024, 2025). "Taken together, preclinical data from mouse and zebrafish models of Scn1a‐related Dravet syndrome is in line with clinical efficacy data for stiripentol and its combinations with other ASMs in this DEE." (PMID 40770908, 2025). "The first preclinical confirmations for antiseizure effects of racemic fenfluramine in models of Dravet syndrome came from pharmacological analysis in an antisense knockdown zebrafish model and an scn1a mutant zebrafish model." (PMID 40770908, 2025). "Our findings highlight the role of deep intronic pathogenic variants in disease and provide additional therapeutic targets for precision medicine in Dravet syndrome and other SCN1A-related disorders." (PMID 39946203, 2025). "Scn1a mutant mice serving as a Dravet Syndrome model with autism spectrum also showed a reduction in delta power." (PMID 41425200, 2025). "Discovery of the SCN1A poison exon known as 20N has led to the first potential disease-modifying therapy for Dravet syndrome in the form of an antisense oligonucleotide." (PMID 39946203, 2025). "An adeno‐associated viral vector‐based approach (ETX101) with cell‐selective expression of a transcription factor upregulating SCN1A expression has entered clinical testing in patients with Dravet syndrome in 2024." (PMID 40770908, 2025). "Here we present a case of Dravet syndrome in which a novel heterozygous deletion involving the promoter region of the SCN1A gene was identified using next-generation sequencing and multiple ligation-dependent probe amplification." (PMID 40903466, 2025). "Significant differences in common genetic variation have also been identified across disease-relevant traits, such as intelligence and longevity, in individuals with SCN1A-related Dravet syndrome." (PMID 40381056, 2025). "Multiple phase 1/2 studies are currently examining ETX101, an AAV serotype 9 (AAV9) gene therapy designed to express voltage-gated sodium channels (NaV1.1) in GABAergic inhibitory interneurons in children with SCN1A-positive Dravet syndrome." (PMID 41007820, 2025). "Preferred adjunctive applications of the KD include genetic epilepsies, such as SCN1A-related Dravet syndrome, TSC1/TSC2-related tuberous sclerosis complex, and UBE3A-related Angelman syndrome." (PMID 40290041, 2025).
Dravet syndrome (continued). "Clinical presentation of patients with pathogenic variants in SCN1A ranges from febrile seizures alone and Genetic Epilepsy with Febrile Seizures Plus (GEFS+) to more severe phenotypes like Dravet syndrome (DS)." (PMID 41151066, 2025). "This category includes disorders attributed to mutations in genes encoding ion channels, such as KCNQ2 in benign familial neonatal seizures, SCN2A in benign familial infantile epilepsy, and SCN1A in Dravet syndrome." (PMID 40217881, 2025). "On the other hand, the ketogenic diet is one of the most effective treatments for Dravet syndrome and has clear protective effects in animal models that lack Scn1a/scn1Lab and Kcna1." (PMID 37594756, 2024). "Patients with Dravet syndrome, a rare genetic encephalopathy, have a higher risk for SUDEP and often have variations in the SCN1A gene." (PMID 38766369, 2024). "The most prevalent form of epileptic encephalopathy is Dravet syndrome (DRVT), which is triggered by the pathogenic variant SCN1A in 80% of cases." (PMID 38110787, 2024). "The aetiology of GEFS+ is more complex than Dravet syndrome, as only ~10% of people with GEFS+ are found to have an SCN1A mutation." (PMID 37594756, 2024). "A retrospective polysomnographic study of children with SCN1A‐Dravet syndrome also found increased sleep instability with an increase in cyclic alternating pattern although normal arousal index." (PMID 39361253, 2024). "Dravet Syndrome is caused by mutations in the SCN1A gene, which encodes the Na + voltage-gated channel subunit Nav1.1." (PMID 39916937, 2024). "Increasing SCN1A expression with antisense oligonucleotides or with AAV‐9‐based gene therapy has been successful in mouse models of Dravet syndrome, and trials in humans are underway." (PMID 37594756, 2024). "We prospectively evaluated clinical and demographic features in individuals with SCN1A positive Dravet syndrome over a 10-year follow-up period identifying predictors of developmental outcome and potential disease biomarkers." (PMID 38229878, 2024). "Mouse models with heterozygous deletion of Scn1a recapitulate key features of Dravet syndrome, including seizures and premature mortality; however, severity varies depending on genetic background." (PMID 38862622, 2024). "Most Dravet syndrome cases are attributed to SCN1A haploinsufficiency, with genetic modifiers and environmental factors influencing disease severity." (PMID 38862622, 2024). "In research using neuronal networks derived from hiPSCs of patients with Dravet syndrome (DS), generalized epilepsy with febrile seizures plus (GEFS+), and febrile seizures with mutations in SCN1A, fragmented NBs were the main phenotypic driver." (PMID 39366380, 2024). "Similar to ETX101, STK-001 is an antisense oligonucleotide designed to enhance the generation of wild-type SCN1A mRNA transcripts to restore inhibitory function in Dravet Syndrome." (PMID 38449810, 2024). "In this research, we used Scn1a KO mice, which served as a mouse model for investigating hereditary epilepsy, specifically Dravet syndrome." (PMID 38674042, 2024). "While a reduction in Nav1.6 can raise the seizure threshold in the animal model of Dravet syndrome, other sodium channel Scn9A can lower the seizure threshold and worsen the disease compared with Scn1a-only mutants." (PMID 39513870, 2024). "The SCN1A mutation leads to either loss of function, including GEFS+ and Dravet syndrome, or gain of function, including familial hemiplegic migraine type 3." (PMID 39119390, 2024). "De novo loss-of-function mutations in SCN1A are leading causes of DEE, especially the Dravet syndrome, which is characterized by intractable febrile seizures." (PMID 39119251, 2024). "Animal studies showed sleep disturbances in SCN8A‐ and SCN1A‐Dravet Syndrome mice models, suggesting a role for voltage‐gated sodium channels in the regulation of sleep." (PMID 39361253, 2024).
Dravet syndrome (continued). "Dravet syndrome (DEE6A) is the most common DEE due to LOF mutations (missense, nonsense, or truncations/deletions) in SCN1A." (PMID 39513870, 2024). "Dravet syndrome (DS), the first described clinical presentation of SCN1A channelopathy, is characterized by severe myoclonic epilepsy in infancy (SMEI)." (PMID 38891831, 2024). "CBD has previously been found to attenuate social deficits in Scn1a +/− mice, which is a mono-genetic mouse model of Dravet syndrome that exhibits autism-like behaviors." (PMID 38784096, 2024). "Culturing an hHBA from Dravet syndrome patient-iPSCs will more closely resemble in vivo developmental changes in structure and function from SCN1A expression." (PMID 38766369, 2024). "Heterozygous mutations within the voltage-gated sodium channel α subunit (SCN1A) are responsible for the majority of cases of Dravet syndrome (DS), a severe developmental and epileptic encephalopathy." (PMID 38283997, 2024). "Nine of the 18 patients had a preceding personal history or notable family history; a neurodevelopmental syndrome was present in six patients, including autism in two and Dravet syndrome (SCN1A positive) in one patient." (PMID 37340737, 2023). "RNA-seq analysis of an Scn1a+/- mouse model of Dravet syndrome identified Gpr55 as a candidate genetic modifier." (PMID 36701411, 2023). "Heterozygous deletion of Scn1a (Scn1a+/-) in mice reproduces the core clinical features of Dravet syndrome, including hyperthermia-induced seizures, spontaneous seizures and poor survival." (PMID 36701411, 2023). "Scn1a+/- mice also exhibit cognitive and behavioral deficits mimicking developmental delays observed in Dravet syndrome patients." (PMID 36701411, 2023). "In contrast, Scn1b−/− mouse somatosensory cortex is haploinsufficient for Scn1a, suggesting an additive mechanism for the severity of the null model via disrupted regulation of another Dravet syndrome gene." (PMID 38425576, 2023). "Dravet syndrome is primarily associated with mutations in the SCN1A gene, encoding the voltage-gated sodium channel Nav1.1, highlighting the genetic underpinnings of epileptic encephalopathies." (PMID 37905295, 2023). "Different from SCN1A LOF variants, SCN2A GOF variants can also cause Dravet syndrome, and oxcarbazepine treatment is usually effective." (PMID 37152433, 2023). "Drug-repurposing approaches for SCN1A-related Dravet syndrome are currently under investigation (i.e., lorcaserin, clemizole, and ataluren)." (PMID 35414300, 2023). "SCN1A (sodium voltage-gated channel alpha subunit 1): Dravet syndrome is a severe, intractable epilepsy syndrome that typically begins in the first year of life." (PMID 37927689, 2023). "For example, Dravet syndrome is a severe developmental and epileptic encephalopathy (DEE) with approximately 80% of cases being caused by mutations in SCN1A, many of which are de novo." (PMID 37834053, 2023). "The first clinical trial of ETX101, called ENDEAVOR (NCT05419492), aims to enroll 22 SCN1A-positive Dravet Syndrome participants aged 6 to 36 months." (PMID 37048615, 2023). "Past studies have noted that genes causing RTT-L are involved in neurodevelopmental diseases such as Dravet syndrome (SCN1A), Pitt–Hopkins syndrome (TCF4), and Huntington’s disease (HTT)." (PMID 37408271, 2023). "In summary, our study shows that ictal vocalizations occur in the Scn1a+/− mouse model of Dravet syndrome." (PMID 36811143, 2023). "The anticonvulsant activity of SB2193 was first assayed in the Scn1a+/− mouse model which recapitulates the characteristic symptoms of Dravet syndrome, including the development of spontaneous seizures and premature mortality." (PMID 37082241, 2023). "In a recent SCN1A study on a cohort of patients with Dravet syndrome it has been demonstrated that SCN1A pathogenic variants did not necessarily acted alone in producing the final phenotype." (PMID 37502687, 2023).
Dravet syndrome (continued). "Our previous study on SCN1A‐positive Dravet syndrome patients also revealed that the seizure was prolonged (>15 minutes) in 29% of patients and was associated with fever in 51% of the total patients at onset." (PMID 36775847, 2023). "Quantification of spontaneous GTCS in the Scn1a+/− mouse model of Dravet syndrome currently relies on manual review of video and/or video‐EEG recordings." (PMID 36811143, 2023). "F1.Scn1a+/- mice, generated by crossing 129.Scn1a+/- mice with wildtype C57BL/6J mice, are seizure-susceptible and exhibit a severe Dravet syndrome phenotype." (PMID 36701411, 2023). "Remarkably, recent investigations on Dravet syndrome estimated that 80% of the syndrome patients carry a mutation in the SCN1A gene that encodes the voltage-gated sodium channel Nav1.1." (PMID 37371302, 2023). "The gene-set collapsing analysis revealed an enrichment (P = 0.010) of rare variants in Dravet syndrome (78 variants in 28 individuals; 2.78 variants per individual) compared with GEL SCN1A controls (81 variants in 45 individuals; 1.8 variants per individual)." (PMID 37006128, 2023). "Pathogenic variations in the sodium voltage-gated channel alpha subunit 1 (SCN1A) gene are responsible for multiple epilepsy phenotypes, including Dravet syndrome, febrile seizures (FS) and genetic epilepsy with FS plus." (PMID 36715146, 2023). "Pathogenic variants in the voltage-gated sodium channel alpha subunit 1 gene (SCN1A) are responsible for multiple epilepsy phenotypes, the most well-recognized of which is Dravet syndrome (DS)." (PMID 36715146, 2023). "In another study, Dravet syndrome was corrected by dCas9-mediated activation of the SCN1A (Sodium Voltage-Gated Channel Alpha Subunit 1) gene in primary mouse hippocampal and cortical neurons." (PMID 36613684, 2022). "Here we show that the cannabis precursor molecule olivetolic acid displayed some anticonvulsant activity against hyperthermia-induced seizures in the Scn1a+/- mouse model of Dravet syndrome." (PMID 34980287, 2022). "We evaluated pure Δ9-THCA against hyperthermia-induced seizures in the Scn1a+/− mouse model of Dravet syndrome." (PMID 33998858, 2022). "For example, multiple deleterious poison exons have been found in SCN1A, leading to Dravet Syndrome (DRVT [MIM: 607208]), a severe neurodevelopmental disorder marked by epileptic encephalopathies." (PMID 36376793, 2022). "A similar effect was observed in P14–16 Scn1a+/− mice (a model of Dravet Syndrome, DS) where CBD (100 mg/kg) managed to increase the temperature threshold for hyperthermia-induced seizures." (PMID 36555823, 2022). "Dravet syndrome is severe childhood-onset epilepsy, caused by loss of function mutations in the SCN1A gene, encoding for the voltage-gated sodium channel NaV1.1." (PMID 35370551, 2022). "To elucidate the role of eEF2K pathway in the etiopathology of Dravet syndrome we generated a new mouse model deleting the eEF2K gene in Scn1a ± mice." (PMID 34980259, 2022). "Consistent with this, the Scn1a+/− mouse model of Dravet syndrome exhibits strain-dependent variable phenotype severity." (PMID 35606653, 2022). "This work provides strong evidence that genetic deletion of eEF2K in the Scn1a ± mice, a mouse model of Dravet syndrome, can rescue both epileptic phenotype and behavioral alterations." (PMID 34980259, 2022). "Currently in clinical trials are ASOs targeting Scn1a (Dravet Syndrome, Clinical Trial #NCT04442295) and Ube3a (Angelman Syndrome, Clinical Trial #NCT04259281)." (PMID 36183905, 2022). "We have recently reported that a series of acidic biosynthetic precursor molecules found in cannabis display anticonvulsant properties in the Scn1a+/− mouse model of Dravet syndrome, including CBGVA and CBDVA." (PMID 36386164, 2022). "Using the Scn1a+/– mouse model of Dravet syndrome, we have found several plant cannabinoids with novel anti-seizure effects." (PMID 36386164, 2022).